AMH (anti-Mullerian hormone)
Diseases named in the same sentence as AMH in open-access papers (continued):
Sharing a sentence is not in itself a finding about the gene and the disease.
cancer (continued). "The most important number of cases of this type of cancer was observed in postmenopausal women (80.49%), when AMH levels dropped to undetectable values." (PMID 30884769, 2019). "The AMH protein was found in some stages in the clinical staging system of cancer according to FIGO (International Federation of Gynecology and Obstetrics) staging." (PMID 30884769, 2019). "We observed a profound reduction in AMH 3 months after the start of cytotoxic treatment in our study of 34 pediatric female cancer patients before and after menarche." (PMID 27537574, 2016). "Studies of ovarian reserves in those whose Anti-Mullerian Hormone (AMH) levels have been measured show that women with cancer have lower levels of AMH prior to receiving chemotherapy than the expected values according to their age group." (PMID 25729417, 2015). "Responses to COS are significantly lower in cancer patients with lower AMH and AFC prior to undergoing chemotherapy with the requirement of higher doses of gonadotropins compared to healthy age-matched women." (PMID 25538933, 2014). "It has been observed that AMH is often lower at the time of a cancer diagnosis." (PMID 40848466, 2025). "In our study, cancer patients who underwent FP had similar AMH levels compared to comparisons." (PMID 38400669, 2024). "AMH, before and after treatment, can be helpful in the management of young women with cancer." (PMID 35626104, 2022). "Anti-Müllerian hormone (AMH) level testing is a useful screening test for assessing ovarian reserve in women at high risk of diminished ovarian reserve, especially for young women with cancer." (PMID 34630317, 2021). "However, studies on the reduction of AMH levels in the m-BRCA women compared to wild type before cancer treatments are controversial, with opposite results." (PMID 34442350, 2021). "The cancer-inhibitory effect of AMH via prevention of cell cycle progression has been documented." (PMID 34316327, 2021). "Thereby AMH was observed to measure the ovarian reserve, suggested that AMH levels may provide a good test to determine the ovarian reserve in cancer survivors." (PMID 32185016, 2019). "In patients with this type of cancer, the serum AMH level reached 1200 ng/mL." (PMID 30884769, 2019). "We aimed to investigate whether the potential presence of the protein concerns menopausal women or those regularly menstruating, and whether is related to cancers with a good or a bad prognosis, as well as what other factors may influence AMH expression." (PMID 30884769, 2019). "Our results may suggest that AMH is a factor which protects the organism against cancer, and should be further investigated as a potential prognosis marker and a therapeutic agent." (PMID 30884769, 2019). "The results of these three studies were similar to that of our study; the AMH levels of the 44 reproductive age cancer patients prior to cancer treatment were lower than that of the non-cancer patients (1.11 [0.08–4.65] ng/ml vs. 3.99 [1.19–8.7] ng/ml; p- value <0.001)." (PMID 32185016, 2019). "Previous studies have shown reduced AMH levels at cancer diagnosis (before treatment) in girls and women, suggesting that other factors, such as impaired general health status, might influence hormone levels." (PMID 27537574, 2016). "Cancer patients have significantly lower AMH after chemotherapy than age-matched controls." (PMID 24666685, 2014). "AMH measurements at cancer diagnosis also predict long-term ovarian function after chemotherapy; so this marker may better predict chemotherapy-related risk to future fertility." (PMID 24406076, 2013). "According to the literature, AMH might reflect remaining ovarian reserve after cancer treatment." (PMID 38381389, 2024). "Additional animal studies are required to confirm and detail the value of AMH in fertility preservation agent, both in its capacity to protect the ovarian reserve during chemotherapy and in the context of ovarian tissue grafting after successful cancer treatment." (PMID 34557157, 2021).
cancer (continued). "Furthermore, it could be useful to elaborate fertility preservation strategies, fertility counseling and future family planning, but we must be careful for now since there is limited data on the prediction of serum AMH on ongoing pregnancy in cancer survivors." (PMID 24666685, 2014). "This study revealed a significant reduction of AMH and AFC in cancer survivors and a dose-dependent relationship between cancer therapies and markers of ovarian reserve." (PMID 35626104, 2022). "Overall findings for all cancer types combined were similar in sensitivity analyses accounting for AMH, FSH, or BMI (data not shown)." (PMID 40493833, 2025). "Endocrine function—indicated by the production of estrogen, follicle-stimulating hormone (FSH), luteinizing hormone (LH), and anti-Müllerian hormone (AMH)—was recovered in most of the cases, validating this protocol as a reasonably reliable tool for cancer survivors." (PMID 39056734, 2024). "Furthermore, AMH and AFC levels were lower among cancer survivors than in the same age control group, although FSH values and menstrual cycles were regular, hence reflecting subclinical follicular depletion." (PMID 35626104, 2022). "Anti-Müllerian hormone (AMH) and FSH levels can be used to assess the antral follicle count to estimate ovarian reserve, although FSH values may vary in cancer survivors; AMH seems to be well correlated with estimation of ovarian reserve." (PMID 35681610, 2022). "Administration of AMH during chemotherapy may provide a synchronistic benefit to women with an AMHR II expressing malignancy, protecting the ovarian reserve whilst the cancer is treated by dual mechanisms." (PMID 34557157, 2021). "The transplantation of ovarian cortical tissue into women who have undergone sterilizing cancer treatment (and thus have no ovarian function) introduces the ovarian tissue into an environment devoid of AMH." (PMID 34557157, 2021). "Worth considering is whether applying AMH in the adjuvant EC therapy in cases of SNPT309G, in the presence of AMHERII, may increase the efficacy of treatment in this type of cancer." (PMID 30884769, 2019). "In analysis of the histopathological type of cancer, the probability of detecting AMH in cells increased in cases of nonatypical hyperplasia, as well as G1 and G2 endometrioid type of EC and, surprisingly in CCA." (PMID 30884769, 2019). "The biological age for cancer patients based on an AMH level of 1.1 ng/ml was 38 years old, and for non-cancer patients 3.99 ng/ml corresponded to 28 years old." (PMID 32185016, 2019). "With respect to those with cancer, there are mixed reports on the predictive value of AMH and AFC compared to patients without a cancer diagnosis." (PMID 25538933, 2014). "Taken together, these findings demonstrate the potential of the AMH‐AMHR2 pathway as a candidate for molecular targeted therapy; however, simply administering AMH to cancers with high AMHR2 expression may not necessarily be appropriate." (PMID 39230026, 2024). "Although some studies have shown that the ovarian reserves of reproductive-age cancer patients before treatment are lower than that of the non-cancer patients, the factors that directly affect AMH levels are still unknown." (PMID 32185016, 2019). "No expression of AMH was observed in the case of other types of cancers." (PMID 30884769, 2019). "Thus, it was conceived that AMH represents a non-toxic substance which may be potentially useful in treating cancers exhibiting AMH receptors." (PMID 30884769, 2019).
tumor (33 papers, 2013 to 2026). "Some studies mention an association between the expression of AMH and possible tumor development." (PMID 39974168, 2025). "In 2021, the investigations in the Endocrinology Department showed normal testosterone and estradiol levels, increased LH and AMH, as well as normal tumor markers (Ca-125, HE4)." (PMID 41515619, 2026). "A GCT was detected by imaging studies, thus, confirming the important role of AMH as a tumor marker." (PMID 41515619, 2026). "Tumor size change was positively and significantly correlated with the change in AMH levels (AMH MidCT-AMH0) in gBRCApv patients (r = 0.93, p < 0.001) but not in WT patients (r = − 0.05; p = 0.84)." (PMID 40220108, 2025). "AMH performs similarly to inhibin B, and using both markers together further improves detection rates for recurrent disease as well as inhibin B; AMH levels correlate with tumor size and disease activity." (PMID 41373846, 2025). "Her oncological monitoring consisted of serial pelvic ultrasounds and tumor markers, including AMH levels." (PMID 34262395, 2021). "A positive correlation was found between the AMH level and gross aggregate tumor mass determined by pathology, as well as between the AMH level and radiographic aggregate tumor mass." (PMID 30884769, 2019). "The ovary containing the tumor and producing high levels of AMH responded to ovarian stimulation in a similar way to the unaffected contralateral ovary." (PMID 30094759, 2018). "AMH elevations are proportional to tumor size and can range from normal reproductive age levels of < 5 ng/mL to levels greater than 100 ng/mL that far exceed normal." (PMID 30094759, 2018). "All dogs with SCT, including dogs with mixed tumours containing neoplastic Sertoli cells, had high (>22 ng/mL) concentrations of AMH, and in the three dogs in which further dilutions were possible, concentrations were found to be elevated from 4X to 1000X." (PMID 26209243, 2015). "Six dogs with SCT or mixed tumours containing SCT had AMH concentrations higher than 22 ng/mL, significantly higher than AMH concentrations in control dogs (P = 0.0004)." (PMID 26209243, 2015). "Nevertheless, follow-up was recommended, because it may take up to 8 years for a microscopic tumor secreting AMH to be detected by imaging studies." (PMID 41515619, 2026). "AMH decay is positively related to tumor size change assessed by imaging in gBRCApv patients." (PMID 40220108, 2025). "Interestingly, we observed a strong positive correlation between tumor size change and AMH levels decrease between baseline and Mid-CT (end of anthracyclines), but this was observed only in the group of gBRCApv patients." (PMID 40220108, 2025). "Furthermore, in human GCT xenograft model, in vivo tumor growth was significantly reduced and plasma AMH levels were significantly decreased in SCID mice after administration of JNK inhibitors and siRNA." (PMID 29549247, 2018). "AMH and inhibin B levels are found to be elevated and can be used as a tumor marker." (PMID 30094759, 2018). "On the other hand, AMH has been described as a tumor suppressor gene in the mouse testis." (PMID 24312319, 2013). "Nevertheless, these findings provide a foundation for future prospective studies with larger populations to better understand the mechanisms of gonadotoxicity and ovarian aging, and to confirm whether tumor response to NAC in gBRCApv patients can be predicted early through serum AMH level changes." (PMID 40220108, 2025). "AMH and inhibin B rose markedly through C6D1 for the non‐PFS6 population, consistent with the finding that these two values are markers for tumour growth." (PMID 41518037, 2026). "There are, however, traditional tumor markers that seem to be unaffected in pregnancy, including lactate dehydrogenase (LDH), Inhibin-B, anti-Mullerian hormone (AMH), carcino-embryonic antigen (CEA), CA-19-9, and human epididymis protein 4(HE4)." (PMID 37999104, 2023).
tumor (continued). "Using data from the HPA database, we found immunohistochemical images of five prognostic signature genes in normal and tumor tissues, including three upregulated genes (ANKLE1, PPP1R27, and AMH) and two downregulated genes (FLRT3 and PPBP)." (PMID 35676660, 2022). "Both serum inhibin and anti-Mullerian hormone (AMH) are elevated in patients with AGCT and can be used as tumor markers for diagnosing AGCT; however, AMH is a more valuable diagnostic tool as its elevation is constant throughout the menstrual cycle." (PMID 33828986, 2021). "In this study, reduced AMH expression correlated only with larger tumor size, but not with prognosis (a." (PMID 36869369, 2023). "While both ERαf/f and ERαd/d ovaries expressed AMH exclusively in the granulosa cells of follicles, ERαd/d ovaries did not express AMH in the tumor cells, indicating that these tumors are not of granulosa cell origin." (PMID 24603706, 2014). "Moreover, mRNA expressions of CA14, RPE65, IGSF1, SLC18 A2 and CPNE6 were significantly lower in PCa samples compared to benign samples, while HJURP, COMP, KRTAP5-1, VGF, SSTR1, LINC01612, NAALADL2-AS2, AMH and ARHGDIG were elevated in tumor samples (p < 0.05)." (PMID 40592939, 2025). "The secondary endpoint was overall survival (OS) and tumor-free survival (TFS) The authors showed a significantly lower POI rate in the GnRHa group compared to chemotherapy only (10.3% vs. 44.5%, p < 0.001) and the AMH recovery rate was better in GnRHa group (15 of 25 vs. 6 of 44; p < 0.001)." (PMID 39055889, 2024). "The prognostic relevance of AMH-IHC remains unclear as in only one study, AMH expression correlated with larger tumor size, but not with prognosis." (PMID 36869369, 2023). "Serum tumour markers like CA 125, CA 15.3, AFP, and SCC are generally not significant during pregnancy, but markers like AMH, CEA, CA 19-9, and HE4 usually do not exhibit increased levels during pregnancy, making them potentially applicable." (PMID 38473031, 2024). "Consistently with AMH, reduced GATA-6 expression correlated with larger tumor size, but not with prognosis." (PMID 36869369, 2023). "There are tumor biomarkers that may be increased, such as CA 15-3, SCC, CA 125, and AFP, and others that are not so much, such as the example of CEA, CA 19-9, LDH, AMH, and HE-4." (PMID 33425755, 2020).
cardiovascular disease (11 papers, 2013 to 2025). "This negative correlation is pathophysiologically supported by clinical and experimental models that seem to implicate low AMH with cardiovascular diseases." (PMID 30288163, 2017). "The vascular cohort, which was free from cardiovascular disease, had higher levels of AMH and tended to have a higher AMH to InhB ratio." (PMID 23940675, 2013). "Besides evaluating the gonadal function, there exist reports indicating AMH as a predictor of renal or cardiovascular diseases in middle-aged or older men; suggesting new insights from a clinical standpoint." (PMID 28715487, 2017). "Thus, AMH, through its effect on inflammation, may reduce cardiovascular disease, COPD, and malignancy and hence overall mortality." (PMID 31511566, 2019). "Our study included only women with normal serum levels of lipids and fasting glucose and women with no family history of cardiovascular diseases because abnormalities in these biochemical parameters and a family history of cardiovascular diseases may impact the plasma levels of CRP and AMH." (PMID 33198782, 2020).
metabolic disorders (6 papers, 2020 to 2025). "The observed correlations with AMH and BMI warrant further investigation, particularly in populations with known micronutrient imbalances or metabolic disorders." (PMID 41497357, 2025). "Finding from this study will provide novel insights into the role of AMH in the pathogenesis of metabolic disorders and further highlight the importance of early prevention and management of metabolic disturbances in women with PCOS." (PMID 38926704, 2024). "Pseudo germ-free mice treated with DHEA+HFD exhibited decreased serum AMH level, glucolipid metabolic disorders and IR." (PMID 36619569, 2022). "There is growing evidence that beyond reproductive implications, AMH may be involved in the pathogenesis of metabolic disorders." (PMID 38926704, 2024).
infection (4 papers, 2019 to 2024). The state of being infected such as from the introduction of a foreign agent such as serum, vaccine, antigenic substance or organism. "The ovarian reserve was not significantly affected in patients recovering from both mild and severe infection in most cases, except one, where the levels of AMH were significantly lower and basal follicle-stimulating hormone (FSH) levels were increased." (PMID 35055804, 2022). "However, the level of AMH, the major inhibitory factor in folliculogenesis, remained unaltered during infection." (PMID 34730391, 2022). "(D) FACS analysis of AMH:EGFP+ cell at day 10 after 5TFs infection." (PMID 31710289, 2019).
gynecologic tumors (2 papers, 2019 to 2023). "This study is the first to introduce AMH into the field of gynecological tumors, aiming to utilize it for EPL." (PMID 37958197, 2023). "Müllerian duct-derived tissues are the main source of various gynecologic tumors and since AMH causes regression of the male Müllerian ducts in male embryos by binding via tissue-specific AMHRII, it has also been proposed to inhibit the growth of gynecologic tumors." (PMID 30884769, 2019).
hematological malignancies (2 papers, 2023 to 2026). "The AMH median levels were 1.4 ± 1.8, 2.5 ± 3.2 and 1.7 ± 1 ng/ml for the hematological malignancy group, solid tumor group and benign disease group, respectively (ng/ml ± interquartile range)." (PMID 37730827, 2023).
kidney disease (2 papers, 2017 to 2025). "In addition, estimated glomerular filtration rate (eGFR) and albumin excretion ratio (AER) were evaluated serially throughout DCCT and EDIC, and we were able to examine whether AMH was associated with these markers of renal disease." (PMID 30766706, 2017).
inflammation (1 paper, 2016). Aberrant reaction of the microcirculation characterized by movement of fluid and leukocytes from the blood into extravascular tissues. "Women with bilateral tubal occlusion showed decreased AMH level, suggesting that chronic pelvic inflammation may diminish ovarian reserve." (PMID 27272680, 2016).
AMH also shares sentences with these, for which no sentence is quoted: Hashimoto thyroiditis (5 papers); prostate carcinoma (5); endocrine disorders (4); acute lymphoblastic leukemia (3); acute myeloid leukemia (2); hyperlipidemia (2); medulloblastoma (2); Micropenis (2); serous cystadenoma (2); sexual dysfunction (2); thrombophilia (2); thyroid (2); abnormal glucose tolerance (1); adrenal hypoplasia (1); adrenoleukodystrophy (1); aging (1); B-cell lymphoma (1); benign tumors (1); bone marrow failure syndrome (1); celiac disease (1); central precocious puberty (1); cerebral infarct (1); cervical incompetence (1); colorectal cancer (1); complete androgen insensitivity syndrome (1); congenital hypogonadotropic hypogonadism (1); cystic teratoma (1); dermatomyositis (1); disorder of sex development (1); Down syndrome (1).
A further 52 diseases each share a sentence with AMH in 1 paper.